CUL4A (cullin 4A)
Description:
Core component of multiple cullin-RING-based E3 ubiquitin-protein ligase complexes which mediate the ubiquitination of target proteins. As a scaffold protein may contribute to catalysis through positioning of the substrate and the ubiquitin-conjugating enzyme. The E3 ubiquitin-protein ligase activity of the complex is dependent on the neddylation of the cullin subunit and is inhibited by the association of the deneddylated cullin subunit with TIP120A/CAND1. The functional specificity of the E3 ubiquitin-protein ligase complex depends on the variable substrate recognition component. DCX(DET1-COP1) directs ubiquitination of JUN. DCX(DDB2) directs ubiquitination of XPC. DCX(DDB2) ubiquitinates histones H3-H4 and is required for efficient histone deposition during replication-coupled (H3.1) and replication-independent (H3.3) nucleosome assembly, probably by facilitating the transfer of H3 from ASF1A/ASF1B to other chaperones involved in histone deposition. DCX(DTL) directs autoubiquitination of DTL. In association with DDB1 and SKP2 probably is involved in ubiquitination of CDKN1B/p27kip. Is involved in ubiquitination of HOXA9. The DDB1-CUL4A-DTL E3 ligase complex regulates the circadian clock function by mediating the ubiquitination and degradation of CRY1. The DCX(ERCC8) complex (also named CSA complex) plays a role in transcription-coupled repair (TCR). A number of DCX complexes (containing either TRPC4AP or DCAF12 as substrate-recognition component) are part of the DesCEND (destruction via C-end degrons) pathway, which recognizes a C-degron located at the extreme C terminus of target proteins, leading to their ubiquitination and degradation. The DCX(AMBRA1) complex is a master regulator of the transition from G1 to S cell phase by mediating ubiquitination of phosphorylated cyclin-D (CCND1, CCND2 and CCND3). The DCX(AMBRA1) complex also acts as a regulator of Cul5-RING (CRL5) E3 ubiquitin-protein ligase complexes by mediating ubiquitination and degradation of Elongin-C (ELOC) component of CRL5 complexes. With CUL4B, contributes to ribosome biogenesis.
Tractability: Small molecule: an approved drug acts on it; a high-quality ligand is known; it has a high-quality binding pocket. PROTAC: UniProt records ubiquitination sites on it; ubiquitination databases record sites on it; its protein half-life has been measured; a small molecule that binds it is known.
Gene: Protein-coding gene on chromosome 13 (113,208,193 to 113,267,108, forward strand). Ensembl gene ENSG00000139842.
Subcellular location (Human Protein Atlas): Nucleoplasm
Pathways (Reactome):
DNA Repair: DNA Damage Recognition in GG-NER; Dual Incision in GG-NER; Dual incision in TC-NER; Formation of Incision Complex in GG-NER; Formation of TC-NER Pre-Incision Complex; Gap-filling DNA repair synthesis and ligation in TC-NER; Recognition of DNA damage by PCNA-containing replication complex; Transcription-Coupled Nucleotide Excision Repair (TC-NER)
Metabolism of proteins: Neddylation
Gene Ontology:
Molecular function: protein binding; ubiquitin ligase complex scaffold activity; ubiquitin protein ligase activity; ubiquitin protein ligase binding
Biological process: cellular response to UV; DNA damage response; positive regulation of protein catabolic process; proteasome-mediated ubiquitin-dependent protein catabolic process; protein ubiquitination; ribosome biogenesis; spermatogenesis; T cell activation; ubiquitin-dependent protein catabolic process via the C-end degron rule pathway; cell population proliferation; epigenetic regulation of gene expression; G1/S transition of mitotic cell cycle; intrinsic apoptotic signaling pathway; negative regulation of adipose tissue development; nucleotide-excision repair; regulation of apoptotic process; regulation of autophagy; regulation of cell cycle phase transition; regulation of cell population proliferation; regulation of cellular response to stress; regulation of DNA-templated DNA replication initiation; regulation of embryonic development; regulation of miRNA-mediated gene silencing; regulation of mitotic cytokinesis; regulation of natural killer cell activation; and 6 more
Cellular component: Cul4-RING E3 ubiquitin ligase complex; Cul4A-RING E3 ubiquitin ligase complex; cytoplasm; nucleotide-excision repair complex; nucleus; nucleoplasm; cullin-RING ubiquitin ligase complex
Genetic constraint (gnomAD): Loss-of-function variants: 9 observed, 48.52 expected, observed/expected ratio (o/e) 0.19, 90% interval 0.11 to 0.32. The upper end of that interval is the gene's LOEUF score, 0.32, which puts it in group 1 of 6, group 1 being the genes least tolerant of losing a copy. Missense variants: 454 observed, 659.85 expected, observed/expected ratio (o/e) 0.69, 90% interval 0.64 to 0.74. Synonymous variants: 295 observed, 260.03 expected, observed/expected ratio (o/e) 1.13, 90% interval 1.03 to 1.25.
Homologues: Orthologues: chimpanzee CUL4A (100% identical), macaque CUL4A (99% identical), mouse Cul4a (95% identical), rabbit CUL4A (95% identical), rat Cul4a (95% identical), guinea pig CUL4A (95% identical), pig CUL4A (94% identical), dog CUL4A (86% identical), tropical clawed frog cul4a (83% identical), zebrafish cul4a (65% identical), Drosophila melanogaster Cul4 (65% identical). Paralogues in human: CUL4B (82% identical), CUL3 (40% identical), CUL1 (31% identical), CUL5 (28% identical), CUL2 (28% identical), ANAPC2 (20% identical), CACUL1 (9% identical).
Diseases named in the same sentence as CUL4A in open-access papers:
CUL4A is named in the same sentence as 74 diseases in open-access papers, as found by Europe PMC text mining. Sharing a sentence is not in itself a finding about the gene and the disease. The quoted sentences say what the papers report.
breast carcinoma (36 papers, 2009 to 2025). "Anti‐tumor immune responses and treatment resistance in breast cancer cells have been linked to CUL4A." (PMID 40384436, 2025). "Clinically, high expression levels of Cul4A in human breast carcinomas are associated with the repression of target genes of p73, indicating that Cul4A is a potent inhibitor of p73 transcriptional activity in cancer." (PMID 33921128, 2021). "The potential predictive value of CUL4A has previously been reported in a panel of 10 breast cancer cell lines, where the expression of CUL4A was associated with higher trabectedin sensitivity." (PMID 32365979, 2020). "Cullin4A (Cul4A) as an oncogene mediates the EMT process in breast cancer cells, which in turn causes metastasis by modifying the regulatory ZEB1 gene." (PMID 32793473, 2020). "The importance of CUL4A in breast cancer chemoresistance was further evaluated by analyzing the association of CUL4A expression levels in breast cancer tissues to patients’ outcomes in public datasets." (PMID 29190892, 2017). "The 13q34 amplification, which is associated with the basal-like breast cancer subtype, has been proposed as one of the mechanism behind CUL4A up-regulation." (PMID 24870930, 2014). "Moreover, we found that CUL4A, an ubiquitin ligase component, was a critical factor bridging H19 lncRNA to MDR1 expression, and a high tumor CUL4A expression was associated with low survival in breast cancer patients treated with chemotherapy." (PMID 29190892, 2017). "The causal role of CUL4A overexpression in tumorigenesis was demonstrated in breast cancer cells, where CUL4A silencing led to reduced cell proliferation, colony formation, cell motility, and tumor development." (PMID 39851492, 2025). "Overexpression of CUL4A protein was initially found in primary breast cancer, suggesting that CUL4A overexpression has closed relation to the development of breast cancer." (PMID 35333690, 2022). "CUL4A demonstrated the potential to promote (epithelial-)mesenchymal transition through the activation of ZEB1 in breast cancer cells." (PMID 34359668, 2021). "In the CUL4A (component of cullin-ring-based E3 ubiquitin protein ligase complex) over expressing tissues such as hepatomas and breast cancer DNMT3B activity was enhanced due to its interaction with CUL4A-NEDD8 resulting in hypermethylation." (PMID 33604794, 2021). "CUL4A was first found to be amplified and overexpressed in primary breast cancers in 1998, and was eventually reported in hepatocellular carcinomas, malignant pleural methotheliomas, and prostate cancers." (PMID 34257560, 2021). "Our findings revealed increased levels of S100A9 and CUL4A leading to a reduced overall and relapse-free survival rate in breast cancer patients." (PMID 32793473, 2020). "Cul4A is reportedly aberrantly expressed in a plethora of cancers including breast cancer, squamous cell carcinoma, pleural mesothelioma, and lung cancer, and its overexpression contributes to tumor progression, metastasis and poor prognosis." (PMID 31632280, 2019). "In breast cancer cells, Cul4A induces an epithelial–mesenchymal transition, and it promotes cancer metastasis by regulating the expression of the EMT regulatory ZEB1 gene." (PMID 31052599, 2019). "Conversely, in vitro and in vivo results have showed that downregulation of CUL4A leads to the inhibition of breast cancer growth." (PMID 28576144, 2017). "Primary breast cancer was the first type of carcinoma in which amplification and overexpression of the CUL4A gene was detected, back in 1998." (PMID 28576144, 2017). "Overexpression of Cul4A is related to breast cancer metastasis 17 and poor prognosis in ovarian cancer." (PMID 26969027, 2016). "And a report found that CUL4A silencing in CUL4A-overexpressing breast cancer cells induced a reduction of cell proliferation and colony formation and decreased the tumor development." (PMID 26460955, 2015).
breast carcinoma (continued). "More interestingly, it was reported that, besides tumor growth and metastasis, CUL4A was involved in conferring breast cancer cells to multiple drug resistance (MDR) by upregulating MDR1/P-gp expression." (PMID 26593394, 2015). "In both analysis the non-transformed cells (HBL100 and 184B5) were within the lower relative expression levels indicating that CUL4A is overall up-regulated in breast cancer cell lines compared with normal mammary epithelial cells." (PMID 24870930, 2014). "Our results support the role of CUL4A as a driver oncogene at the 13q34 amplification in basal-like breast cancer." (PMID 24870930, 2014). "The overexpression of the CUL4A E3 ubiquitin ligase has been related to tumor aggressiveness and poor clinical outcome in breast cancer." (PMID 24870930, 2014). "In breast cancer, a recent functional analysis of CUL4A has revealed a pivotal role of the gene in regulating the metastatic behavior of breast cancer cells." (PMID 24870930, 2014). "Thereby CUL4A would constitute a promising target for therapeutic intervention and our data reinforce its clinical value in basal-like breast cancers." (PMID 24870930, 2014). "In this study we have evaluated in vitro and in vivo the functional significance of CUL4A down-regulation and up-regulation in basal-like breast cancer models that exhibit features resembling those found in primary breast tumors." (PMID 24870930, 2014). "The CUL4A E3 ubiquitin ligase is involved in the regulation of many cellular processes and its amplification and/or overexpression has been observed in breast cancer." (PMID 24870930, 2014). "Our results show that CUL4A would contribute to the tumorigenicity of basal-like breast cancers through the modulation of cell growth and anti-tumor immune response." (PMID 24870930, 2014). "For the first time, we report a putative role of CUL4A in bypassing the immune system in breast cancer through the down-regulation of several molecules involved in the anti-tumor immune surveillance." (PMID 24870930, 2014). "In summary, we propose CUL4A as an important contributor to the development and progression of basal-like breast cancers." (PMID 24870930, 2014). "We first transfected vectors carrying CUL4A and specific shCUL4A into breast cancer cells and corresponding Adr cells respectively." (PMID 24368600, 2013). "Lastly, immunohistochemistry in breast cancer tissues showed that P-gp expression had a positive correlation with the expression of CUL4A and ERK1/2." (PMID 24368600, 2013). "In summary, our work confirms that CUL4A regulates the expression of MDR1 via an ERK1/2 dependent signaling pathway in breast cancer cells, which is consistent with their alterations in cellular multidrug resistance in vitro." (PMID 24368600, 2013). "Our results suggest that overexpression of CUL4A in breast cancer is responsible for the required resistant to P-gp substrate drugs through regulation of MDR1/P-gp expression." (PMID 24368600, 2013). "Noticeably, the amplification and overexpression of CUL4A was also reported in primary breast cancers a few years ago." (PMID 19995430, 2009). "GLS, YY1AP1, FBXO22, KLC1, CUL4A, KITLG, and CYRIB are changed by AS that may be linked to the emergence of breast cancer." (PMID 40384436, 2025). "Previous studies showed that CUL4A was overexpressed in breast cancers 22-24, 28, suggesting that Cullin4-RING Ligase (CRL4) might play an important role in breast carcinogenesis." (PMID 35280675, 2022). "In addition, analysis of a dataset in GEO (GSE52544) with CUL4A depletion in breast cancer cells indicated that 7 molecular pathways affected by CUL4A knockdown were converged to those with H19 knockdown." (PMID 29190892, 2017). "CUL4A also contributes to basal-like breast cancers via activation of the Ras signaling pathway." (PMID 26840256, 2016).
breast carcinoma (continued). "Interestingly, in previous studies we observed increased sensitivity to trabectedin in breast cancer cell lines exhibiting high levels of CUL4A in combination with a “BRCAness” status." (PMID 24870930, 2014). "CUL4A expression varied across the breast cancer cell lines." (PMID 24870930, 2014). "CUL4A silencing in CUL4A-overexpressing basal-like breast cancer cells induced a reduction of cell proliferation and colony formation in short-term assays and long-term soft agar assays and decreased the tumor growth rate of cells injected into mammary glands of nude mice." (PMID 24870930, 2014). "In this regard our data suggest that the 13q34 amplification could be a robust biomarker for identification of up to 20% basal-like breast cancer patients that might eventually benefit from CUL4A-targeted therapy." (PMID 24870930, 2014). "Since the 13q34 amplification and/or CUL4A overexpression is more frequent in BRCA1-associated and basal-like primary breast tumors we selected the BRCA1-null HCC1937 and the 13q34 amplified MDAMB157 cell lines to further characterize CUL4A function in breast cancer progression." (PMID 24870930, 2014). "The potential therapeutic option of CUL4A- targeting in certain subtypes of breast cancer has also been discussed in a recent study reporting a fundamental role of CUL4A in regulating the metastatic behavior of breast cancer cells." (PMID 24870930, 2014). "In addition we found that, although not exclusively, the 13q34 amplification would be one of the mechanisms triggering CUL4A overexpression in breast cancer." (PMID 24870930, 2014). "In the research described in this report we aimed to clarify whether CUL4A participates in multiple drug resistance (MDR) in breast cancer cells." (PMID 24368600, 2013). "CUL4A, a newly found oncogene, is amplified in breast cancers." (PMID 24368600, 2013). "In breast cancers, over-expression of CUL4A strongly correlates with poor prognosis." (PMID 24368600, 2013). "Our results suggest that CUL4A may play a role in breast cancer progression, based on its amplification and significant overexpression, previously reported in breast malignancies, as well as in other carcinomas." (PMID 19995430, 2009). "We conclude that 13q34 amplification may be of relevance in tumor progression of basal-like breast cancers by inducing overexpression of CUL4A and TFDP1, which are both important in cell cycle regulation." (PMID 19995430, 2009). "As some of these features are basal-cell markers (such as EGFR, CK5, P-Cadherin), CUL4A may play an important role in the biology of basal-like breast cancers." (PMID 19995430, 2009). "Indeed, many E3 ligases including CUL4A were seen overexpressed in breast cancers 22-24." (PMID 35280675, 2022). "Mechanistically, H19 promotes expression of Cullin 4A (CUL4A), a ubiquitin ligase component, which in turn enhances expression of ABCB1/4 genes that encoded MDR1/4 proteins, two members of the ATP-binding cassette family highly upregulated in several carcinomas, including breast cancer." (PMID 35955440, 2022). "Furthermore, CUL4A remained amplified in breast carcinomas, and these data may indicate that dynamic changes in the expression of the CRL4A complex contribute to breast oncogenic properties." (PMID 34240781, 2021). "Compared to Cul4A, findings linking Cul4B to cancer are less common, however it was still found to be overexpressed in colon cancer, cervical cancer, lung cancer, esophageal cancer, and breast cancer, with its overexpression closely related to tumor stage, invasion and metastasis." (PMID 31632280, 2019). "Interestingly, Cullin4A gene is amplified in breast cancers, and is deregulated in lung cancer, information about deregulation of Cul4A/B in HNSCC is currently unknown." (PMID 30410671, 2018).